TNFSF4 (TNF superfamily member 4)
Diseases named in the same sentence as TNFSF4 in open-access papers (continued):
Sharing a sentence is not in itself a finding about the gene and the disease.
cancer (104 papers, 2011 to 2026). A tumor composed of atypical neoplastic, often pleomorphic cells that invade other tissues. "GeneMANIA analysis revealed various interactions—including Tph2-CXCR4 and Sspo-TNFSF4—among the genes whose expression in human metastasizing cancer cells or the mouse brain stroma was associated with metastasis." (PMID 28210624, 2017). "In addition, high TNFSF4 expression is associated with better overall survival probability (HR = 0.71) in cancer patients treated with immunotherapies." (PMID 41310721, 2025). "Tnfsf4, also known as tumor necrosis factor ligand superfamily member 4, is an inflammatory factor that has been associated with various inflammatory diseases and cancers." (PMID 37504294, 2023). "For PDCD1 and TNFSF4, rs36084323 was associated with cancer risk." (PMID 36189300, 2022). "TNFRSF4 and TNFSF4 mutations in cancers were rarely reported." (PMID 34900670, 2021). "In contrast, a uniform negative association with PEBP1/STK11 co-expression was found in most of the genes encoding TNF ligands (ENFSF13B, TNFSF4, TNFSF9, TNFSF14, TNFSF18, and TNFSF15) in almost all cancer types." (PMID 40806276, 2025). "Immune checkpoint analysis revealed that basically all the checkpoints were upregulated in the low-risk group except for CD44, TNFSF4/9, and CD276 (marker of cancer stem cell)." (PMID 38341588, 2024). "The findings reveal that COMP was positively correlated with a majority of immune inhibitors and stimulators in several cancers, with TNFSF4, an immune stimulator, and HAVCR2, an immune inhibitor, exhibiting the strongest correlation with COMP." (PMID 36551305, 2022). "Recent studies have shown that stimulation of OX40, the ligand of TNFSF4, is helpful for therapeutic immunization strategies for cancer." (PMID 35836192, 2022). "For single immune checkpoint gene, the immune stimulator HMGB1 correlated positively with KIF11 in all human cancer types, and TNFSF4, BTN3A1, BTN3A2, and ENTPD1 correlated positively with KIF11 in most human cancer types." (PMID 36742345, 2022). "Other immune checkpoint-related genes as CD28, TGFBR1, and TNFSF4 (OX40L) have been frequently reported to engage in cancer immune regulation in ICI research." (PMID 34897033, 2021). "In addition, we found that T cells with higher expression of OX40 ligand (TNFSF4) contributed to NK cell migration toward cancer cells." (PMID 36694264, 2023). "Interestingly, CD276, NRP1, and TNFSF4 expressions were significantly negatively correlated with SHC1 in various cancers." (PMID 35601500, 2022). "LINC02672 was significantly correlated with the expression of IDO1, NRP1 and TNFSF4 in pan‐cancers, and it was significantly associated with the abundance of CD56 bright natural killer cells, mast cells, and immature dendritic cells in pan‐cancers." (PMID 33797188, 2021). "TNFSF4 is a binding partner of OX40, and in cancer treatment, the OX40-TNFSF4 pathway has been found to influence immune tolerance." (PMID 36733811, 2022). "The OX40, that is, “tumor necrosis factor receptor superfamily, member 4” (CD134, TNFRSF4) and its ligand OX40L,” “tumor necrosis factor (ligand) superfamily, member 4” (OX40L, CD252, TNFSF4), are fundamental in augmenting the immune response against cancer cells." (PMID 36652956, 2023). "Moreover, our analyses revealed correlations between EMT and immune checkpoints in early-stage LUAD, such as CD200, TNFSF4 and SIRPA, which have also been demonstrated in other types of carcinomas." (PMID 35645555, 2022). "Notably, TNFSF4 and ENTPD1 are positively correlated with MATN3 across most cancers." (PMID 41004439, 2025). "Additionally, a higher expression of TNFSF4 in T cells, not NK cells themselves, contributed to better NK cell migration toward cancer cells in assays in vitro." (PMID 39201666, 2024).
cancer (continued). "The analysis of 46 immunostimulatory genes in pan-cancer showed that HSP90B1 expression was positively correlated with CD40, CD270, PVR, MICB, ULBP1, TNFSF4, while exhibiting a negative correlation with CD48 and CD40LG in most cancers." (PMID 38243263, 2024).
infection (37 papers, 2008 to 2025). The state of being infected such as from the introduction of a foreign agent such as serum, vaccine, antigenic substance or organism. "Previous studies have also suggested that TNFSF4 expression is upregulated during infection and that the presence of genetic polymorphisms within the TNFSF4 locus is associated with the risk of developing immune-related diseases and determining stem cell transplantation outcomes." (PMID 33374839, 2020). "TNFSF4 mediates adhesion of activated T cells to endothelial cells during the infection, which is a key process to induce the expression of leukocyte adhesion molecules (E-selectin, VCAM-1) and secretion of proinflammatory cytokines." (PMID 33374839, 2020). "Our results indicate that SIRT6 binds to promoter region of TNFSF4 under basal conditions, which was increased upon infection with SIRT6 adenovirus." (PMID 27249230, 2016). "TNFSF4/5/10 and TNFRSF4/8/9/13B were influenced during DTMUV infection and all these factors function as important proinflammatory genes and play vital roles in the inflammatory response." (PMID 35585616, 2022). "Additionally, TNFSF4-TNFSRF4 interactions alter the differentiation and activity of regulatory T cells and TNFSF4 mediates adhesion of activated T cells to endothelial cells during infection, inducing secretion of proinflammatory cytokines." (PMID 39227786, 2024).
renal disorder (2 papers, 2013 to 2017). "Other significant findings include the association between renal disorder and TNFSF4, malar rash and FCGR2A and hematological disorder and variation in the IL21 gene." (PMID 28619073, 2017). "In conclusion, our study provided further potential evidence for TNFSF4 as a risk factor contributing to renal disorder in SLE." (PMID 23936824, 2013). "Also, the previously identified association between genetic variation in the TNFSF4 gene and renal disorder was replicated in the discovery cohort." (PMID 28619073, 2017). "A recent phenotypic association study of genetic susceptibility loci in SLE suggested that TNFSF4 gene might be useful to predict renal disorder in lupus patients." (PMID 23936824, 2013).
TNFSF4 also shares sentences with these, for which no sentence is quoted: atopic dermatitis (20 papers); lymphoma (15); viral infection (10); Allergy (9); allergic asthma (8); diabetes (8); ovarian carcinoma (8); colitis (6); coronary artery disease (6); allergic rhinitis (4); colorectal cancer (4); dermatitis (4); eczema (4); eosinophilia (4); gastric cancer (4); liver cancer (4); Type 1 Diabetes (4); allergic conjunctivitis (3); ankylosing spondylitis (3); Arthritis (3); Behcet disease (3); food allergy (3); graft versus host disease (3); helminth infection (3); inflammation (3); Insulin resistance (3); leukemia (3); oral cancer (3); prostate carcinoma (3); Sepsis (3).
A further 120 diseases each share a sentence with TNFSF4 in 2 papers or fewer.